TNF (tumor necrosis factor)
Diseases named in the same sentence as TNF in open-access papers (continued):
Sharing a sentence is not in itself a finding about the gene and the disease.
Cirrhosis (continued). "Enterocytes: IPA analysis showed significant activation of inflammatory pathways (TNF, IFNG), PPARG/A with gut-liver signaling pathways (FGF21, IGF1R, CREBP) and fatty acid and lipid oxidation in compensated cirrhosis versus controls." (PMID 38369527, 2024). "Stem cells: Compared to controls, LXR/RXR and RICTOR signaling pathways were activated in compensated cirrhosis but inflammatory pathways (IFNG, TNF) were downregulated." (PMID 38369527, 2024). "Importantly, TNF-α may be associated with disease severity; more advanced phenotypes (i.e., NASH or NAFLD-related cirrhosis) seem to be associated with higher circulating TNF-α, which may also link NAFLD with extrahepatic manifestations, such as CVD and malignancies." (PMID 37407724, 2023). "In comparison to the placebo group, 90 days of rifaximin treatment decreased the plasma levels of tumor necrosis factor alpha (TNF-α) and circulating neutrophil TLR-4 expression in patients with cirrhosis and hepatic encephalopathy." (PMID 37237771, 2023). "In patients with cirrhosis, rifaximin has been demonstrated to increase mean arterial pressure and GFR, while decreasing plasma endotoxin, serum interleukin-6, and serum tumor necrosis factor-α." (PMID 37626668, 2023). "According to qRT-PCR, levels of the proinflammatory cytokines (IL-1β, TNF-α, and IL-6) were extremely increased in ACLF patients compared with those in HCs and cirrhosis patients, which suggested a hyperinflammatory state in the liver of ACLF patients." (PMID 35629036, 2022). "A previous study on cytokines in cirrhosis demonstrated that HBV- and HCV-cirrhosis affected CXCL10, CXCL8, M-CSF and TNF serum levels." (PMID 36230823, 2022). "Some studies focused on the secretion of IL-1, IL-6, TNF, TGF-β, and other cytokines due to splenomegaly, which leads to the formation of cirrhosis." (PMID 36211271, 2022). "Patients with cirrhosis often present with chronic inflammation and high coagulability, and the association between the RDW and inflammation may be because the elevation of inflammation factors, such as TNF and IL, aggravates microcirculation hypoxia, resulting in hemodynamic changes." (PMID 36387035, 2022). "The upregulation of intestinal TNFα-TNFR signals and phosphorylation of intestinal MLCK is involved in the pathogenesis of intestinal barrier dysfunction and disease progression in cirrhosis." (PMID 33513830, 2021). "To conclude, we provide evidence entirely from human experimentation that demonstrates PGE2, acting via its EP4 receptor, downregulates monocyte TNFα and IL6 production in decompensated cirrhosis and reduces monocyte HLA-DR expression." (PMID 34825153, 2021). "It is assumed that cytokines play central roles in the progression from chronic liver injury to fibrosis/cirrhosis and several pro-inflammatory cytokines (such as IL6, and TNFα) correlate with disease severity." (PMID 32813194, 2020). "The oxidative stress promotes hepatocyte cell death and activation of inflammatory pathways, including expression of the pro-inflammatory cytokine tumor necrosis factor (TNF), that lead to advanced fibrosis and cirrhosis." (PMID 31456946, 2019). "Some studies have shown potential effects of Cit on reducing inflammatory markers such as tumor necrosis factor α (TNF-α) and interleukin-6 (IL-6), which can prevent development of disease to severe conditions such as NASH and cirrhosis." (PMID 30767788, 2019). "Surprisingly, TNF-alpha and MCP-1 levels were both lower in patients with compensated cirrhosis than in healthy subjects." (PMID 30941129, 2019). "Patients with decompensated cirrhosis were recently demonstrated to have high levels of plasma PGE2, which impaired LPS-stimulated TNF production in healthy monocytes ex vivo." (PMID 30873165, 2019).
Cirrhosis (continued). "TNF-α plays an important role in the pathogenesis of both HIV and HCV infections, and it has been related to AIDS progression and the development of cirrhosis." (PMID 30400258, 2018). "Thalidomide can modulate the TNFα-NFκB and iNOS pathway, which involve in the pathogenesis of hepatopulmonary syndrome (HPS) and muscle wasting in cirrhosis." (PMID 28009008, 2016). "IL-12, IL-6 and TNF-α levels were higher in alcoholic cirrhosis (p < 0.05 for all), while IL-1β and IL-10 levels were comparable between patients with alcoholic or HCV cirrhosis." (PMID 26343741, 2015). "Alcoholic hepatitis, chronic hepatitis B and hepatitis C, cirrhosis, CCA, HCC, and experimental injury of liver can increase TNF-α expression." (PMID 26508814, 2015). "Despite increased phenotypical markers of T cell activation in cirrhosis, we observed a reduced fraction of T cells with cytokine responses to SEB as well as reduced TNF-α production in CD4+ and CD8+ T cells after stimulation with SEB." (PMID 23446058, 2013). "Cirrhotic rats had significantly higher levels of proinflammatory cytokines including TNF-α, IL-1β and IL-6, and soluble ICAM-1, which have been shown to play important roles in development of cirrhosis." (PMID 22022478, 2011). "In patients with advanced cirrhosis, we actually determined the TNF-alpha and xCT mRNA of monocytes, and evaluated the correlation between the plasma L-Cys/L-Glu ratio and TNF-alpha." (PMID 21858100, 2011). "This included pro-inflammatory pathways such as TNF–TNFRSF1A/B, MIF–CD74+CD44, and several MHC class II–CD4 interactions, suggesting that macrophages play an active antigen-presenting and inflammatory role during cirrhosis." (PMID 41153430, 2025). "This is fully in agreement with our data, where patients in the BCLC B group had a lower level of this cytokine compared to the other groups and consequently a higher TNF-α/IL-10 ratio of 14.7 versus 2.4 and 3.3 in the BCLC A and cirrhosis groups, respectively." (PMID 41379186, 2025). "Its function is to transport LPSs to effector immune cells, and the decontamination of the intestine with norfloxacin decreases the risk of bacterial infections, decreases circulating levels of TNF-α and LBP, and improves the hemodynamic status of patients with advanced cirrhosis." (PMID 39337069, 2024). "The authors also noted a trend of increasing IL6 and TNFα concentrations from controls to cirrhosis to HCC but attribute the lack of significance to the small sample size." (PMID 37055022, 2024). "Similarly, TNF secretion is increased in the MLN and serum of patients with cirrhosis has been reported to predict post-transplant bacterial infection." (PMID 38191517, 2024). "Additionally, the proportion of CD4 T cell-TNFAIP3, CD8 T cell-TNF (effector CD8 T cells), and CD8 T cell-CD53 increased, while the proportion of Treg cells decreased from HBV infection to cirrhosis." (PMID 38116005, 2023). "As a result, TNF-α-induced MCP-1 expression may be an essential component in the progression of liver damage and cirrhosis." (PMID 36110559, 2022). "In addition to supporting the previous observation regarding the crosstalk between hepatic SIRT1 and TNFα, this study suggests a link between SIRT1−TNFα crosstalk and intestinal SIRT1-related effects and renal dysfunction of cirrhosis." (PMID 33513830, 2021). "Recently, a clinical study showed that there are no beneficial effects of anti-TNF agent use for development of cirrhosis, non-alcoholic fatty liver disease (NAFLD) or NASH in patients with immune-related diseases." (PMID 34305946, 2021). "Detailed analyses of the distinct subsets revealed that TNF-α/IL-6 production in response to LPS was decreased in both CD14+HLA-DR+AXL+ monocytes and M-MDSCs when compared with CD14+HLA-DR+AXL− monocytes from patients with cirrhosis and HC." (PMID 31822557, 2020).
Cirrhosis (continued). "Consistent with previous studies, our results show decreased baseline frequencies of either IFN-γ- or TNF-α-producing NK (CD56dim and CD56bright) cells in patients with cirrhosis regardless of their HCV status." (PMID 32161581, 2020). "In our cohort of patients with chronic liver disease, LPS-induced TNF production was not impaired in patients with decompensated cirrhosis overall, but was significantly reduced in patients who died during 6 months follow up and correlated with time to death." (PMID 30873165, 2019). "In order to confirm the risk factors of RFS in HCC patients, Cox proportional hazard analysis was performed with clinical factors (age, gender, maximum tumor size, MVI, cirrhosis, differentiation, HBsAg status, and AFP) and preoperative serum IL6, IL8, and TNF-α levels." (PMID 31781194, 2019). "Additionally, HIV/HCV-coinfected patients with advanced cirrhosis (LSM ≥25 kPa) had the lowest plasma values of cytokines related to Th1 (IL-2 and TNF-α) and Th17 (IL-17A) response." (PMID 30400258, 2018). "Additionally, patients with cirrhosis who had LSM ≥25 kPa showed the lowest values of plasma cytokines [Th1 (IL-2 and TNF-α) and Th17 (IL-17A)]." (PMID 30400258, 2018). "Thus, it is possible that patients with LSM ≥25kPa had a lower production of IL-2, TNF-α, and IL-17A due to the taxing effect of bacterial translocation on the immune system, which may induce immune dysfunction and a lower production of key cytokines during severe cirrhosis." (PMID 30400258, 2018). "TNF-α levels were elevated in ALD patients with cirrhosis compared to ALD patients without cirrhosis (p < 0.05)." (PMID 26343741, 2015). "Finally, we confirmed that the TNF-alpha mRNA of CD14 monocytes, isolated from patients with advanced cirrhosis, was at a higher level than in healthy controls." (PMID 21858100, 2011). "A switch to a Th1 pattern of tumor necrosis factor alpha (TNF-a) and interferon-gamma (IFN-γ) production and a concomitant depletion of Th17 in the native layer has been reported in a rat model of liver cirrhosis as cirrhosis progresses into the decompensated phase." (PMID 38191517, 2024). "In experimental models of cirrhosis, intestinal CD103+ DCs are activated when the decompensation of liver function (ascites) occurs, and there is an expansion of pro-inflammatory CD4+ DCs, which favors the increase in the production of TNF and the increase in phagocytosis and migration capacity." (PMID 39337069, 2024). "Notably, priming neutrophils from patients with cirrhosis with TNF-α does not increase their response to fMLF as is usually the case with healthy donor neutrophils." (PMID 37822786, 2023). "Patients with cirrhosis have lower levels of high-density lipoprotein (HDL) cholesterol and apolipoprotein A1, which further decrease upon decompensation, correlating with increased levels of TNF-α, IL-8, IL-6 and severe bacterial infection, and predicting patient mortality." (PMID 37822786, 2023). "In addition, the anti-TNF-α agents, such as infliximab and adalimumab, potently suppressed IL-12/IL-23 production by inflammatory macrophage by activating FcγRs, but anti-TNF-α agent did not play a beneficial effect for development of cirrhosis." (PMID 37325634, 2023). "In concordance with this published data, we detected in cirrhosis and HCC that with dysbiosis, a measurable shift occurs toward a systemic Th1/Th17 proinflammatory cytokine phenotype, characterised by increased levels of IFN- γ, TNF-α, IL-6 and IL-17 amongst others." (PMID 33858327, 2021). "Similarly, plasma from patients with acutely decompensated, but not compensated, cirrhosis suppressed LPS-induced TNF production by healthy monocytes." (PMID 30873165, 2019). "However, the pathogenic roles of recruited muscular macrophages and activated TNFα-NFκB-iNOS cascades have not yet been explored in muscle wasting of cirrhosis." (PMID 28009008, 2016).
Cirrhosis (continued). "Increased production of TNF-α may play an important role in the process of bacterial translocation in rats with cirrhosis and ascites because TNF-α blockade is able to downregulate it without increasing the incidence of systemic infections." (PMID 21152120, 2010). "Increased production of TNFα may play an important role in the process of bacterial translocation in rats with cirrhosis and ascitis because TNFα blockade is able to downregulate it without increasing the incidence of systemic infections." (PMID 19014418, 2008). "Similarly, patients with cirrhosis undergoing selective intestinal bacterial ablation with norfloxacin show a reduction in serum concentrations of pro-inflammatory cytokines TNFα, IFNγ, and IL12 and reduced activation of NF-Κb as measured by ELISA and western blot respectively." (PMID 37055022, 2024). "Our findings indicate that the effect of these SIM may either not translate from in-vitro to patients with cirrhosis, or the impact of TNF-α and IL-1β could be limited to their secretion by astroglial cells and thus not translate to measurably different levels in cubital vein blood." (PMID 39656322, 2024). "Unlike other studies, serum TNF-α and CRP were not increased, possibly due to the early stage of cirrhosis and cohort homogeneity, as well as differences in cirrhosis etiology." (PMID 39850960, 2025). "Nonetheless, the contribution of the crosstalk between intestinal and renal TNF and SIRT1 signals in the severe renal dysfunction of cirrhosis has not yet been explored." (PMID 33513830, 2021). "Consistent with the observations in patients with cirrhosis ex vivo, AXL-expressing THP-1 cells produced less TNF-α and IL-6 in response to LPS when compared with non-transduced THP-1 cells." (PMID 31822557, 2020). "Growing evidences revealed higher levels of IL6, TNFα, IL1β, and IL10 in HCC patients with cirrhosis compared with those infected with HBV or HCV in the absence of cirrhosis." (PMID 32164265, 2020). "In contrast, CD4+ and CD8+ T cells of patients with acutely decompensated cirrhosis or with ACLF did not respond to stimulation with PMA/ionomycin with induction of IFN-γ and TNF-α." (PMID 33574809, 2020). "MAIT cells from patients with cirrhosis produced more IL-17 and granzyme B than those from control individuals, whereas the frequency of IFN-γ+ or TNF+ MAIT cells was high, but not different between the two groups." (PMID 29858567, 2018). "Yet we observed presence or absence of cirrhosis in HCC patients not reflecting expression of IL-6, IL-27, TNF-α, and VEGF." (PMID 25908103, 2015). "Though, again adiponectin and TNF-alpha stood out as significantly different between ALD patients with and without cirrhosis." (PMID 24988316, 2014). "However, retrospective studies of patients receiving anti-TNFα for immune-related diseases reported no reduction in the incidence of new onset NAFLD, NASH, or cirrhosis." (PMID 37200978, 2023). "In addition, circulating IL-6 in cirrhosis with PVT was further elevated compared to that in cirrhosis with non-PVT pigs, whereas nonsignificant alterations were identified as regards serum IL-8 and TNF-α levels." (PMID 32351989, 2020).
Allergy (230 papers, 2005 to 2026). An allergy is an immune response or reaction to substances that are usually not harmful. "Among eight patients exposed previously to TNF-antagonist, three discontinued due to secondary loss of response, one due to high antibody concentration, and four due to allergy." (PMID 37908975, 2023). "The association between allergic diseases and poor oral health is related to increased levels of inflammatory cytokines, such as interleukin (IL)-1β, IL-6, and tumor necrosis factor-α." (PMID 36833618, 2023). "Consistent with this, studies showed that cytokine variants including TNF-α 308 A → G, IL-13 and IL-4RA as well as genetic variation in IgE receptor were associated with predisposition to drug-induced allergy." (PMID 35307016, 2022). "PMA/A23187 acts on mast cells and induces them to produce IL-1β, IL-6, TSLP, and TNF-α, causing allergy-related inflammation." (PMID 34681651, 2021). "TNF-α is a hallmark cytokine in both diseases, allergy and bacterial infection, and thus a relevant readout to determine the efficacy of the anti-inflammatory drug budesonide." (PMID 32899549, 2020). "TNF-α has been involved in the activation of T cells and the promotion of oral tolerance and reduced production of TNF-α has been observed in allergic infants or those at high risk of developing allergy after stimulation with food allergens." (PMID 26907333, 2016). "Compelling evidence, herein, demonstrates that B-ADAM10, ADAM17, and TNF are differentially regulated in Th1 and Th2-dominated immune responses and directly influence host susceptibility to allergy and IgE production." (PMID 25933166, 2015). "On the contrary cell system, we can detect allergy associated cytokines such as TNF-α, IL-4, IL-13 by RT-PCR in vivo system." (PMID 26317642, 2015). "The levels of pro-inflammatory cytokines (IL-1β, IL-6, TNF), anti-inflammatory cytokine (IL-10), Th2-type cytokines associated with allergy (IL-4, IL-13, IL-33) and Th1-type cytokine (IFN-γ) were analysed from the treated skin sites of all groups." (PMID 25123235, 2014). "Reasons for the switch from a first anti-TNF-alpha antibody to a second anti-TNF-alpha antibody in these patients were allergic reactions (n = 30; 65.2%), intolerance (n = 3; 6.5%) and loss of response (n = 13; 28.3%)." (PMID 24932476, 2014). "Inhibition of TNF-α expression can reduce the risk of allergic reactions." (PMID 38835658, 2024). "Activation of blood cells by the allergen caused production of minor amount of TNF-α and quite a large amount of IL-8 playing a leading role in allergy development, whereas activation by endotoxin caused notable production of pro-inflammatory cytokine TNF-α, thus decreasing the cytokine ratio." (PMID 30412632, 2018). "Finally, IL-10 can be produced by T cells and is able to diminish PMN influx by inhibition of expression of proinflammatory chemokines, NF-κB (via I kappa kinase), and TNF, as well as modulate cells and effector functions associated with an allergic response." (PMID 16026622, 2005). "Among Th2-cell subtypes, TNF-α-rich inflammatory Th2 (iTh2) cells may be developed by stimulation of dendritic cells with Th2 adjuvants associated with allergens or thymic stromal lymphopoietin (TSLP) often found in inflammatory tissues in allergic diseases." (PMID 23283296, 2008). "KEGG pathway analysis suggests mainly the TNF signaling pathway to be important in the resolution of CM allergy." (PMID 40929127, 2025). "Allergy symptom scoring (gastrointestinal, respiratory, skin, and systemic allergy reflections); inflammatory factors (TNFα/IL-1β/IL-6/IL-10); antibodies (IgE/IgG2); efficacy in eczema reduction." (PMID 40529417, 2025). "Meanwhile, meta-analyses in related conditions such as osteoarthritis and obesity demonstrate ginger’s capacity to significantly reduce c-reactive protein (CRP) and TNF-α, indirectly supporting its anti-inflammatory potential in allergy." (PMID 41305557, 2025).